ENSG00000212228
Synonyms: LOC124900380
Gene: Small nucleolar RNA gene on chromosome 16 (11,274,113 to 11,274,236, reverse strand). Ensembl gene ENSG00000212228.
Gene Ontology:
Biological process: RNA processing
Cellular component: nucleolus
Homologues: Paralogues in human: SNORA48 (81% identical), SNORA48B (80% identical).